EYS (EGF-like photoreceptor maintenance factor)
Diseases named in the same sentence as EYS in open-access papers (continued):
Sharing a sentence is not in itself a finding about the gene and the disease.
retinal disease (8 papers, 2017 to 2026). "A chart review was performed to identify RP patients who had mutations in the EYS gene, identified through the Invitae Inherited Retinal Disease Panel, which evaluates more than 300 genes." (PMID 39588395, 2024). "We, and others, have previously generated and characterized zebrafish eys knock-out mutants, and presented the zebrafish as a suitable model to study EYS-associated retinal disease." (PMID 34502064, 2021). "EYS mutations are associated with arRP and arCRD, both of these retinal diseases lead to photoreceptor death and vision loss." (PMID 28378834, 2017). "The purpose of this study was to identify pathogenic EYS variants, to determine the clinical/genetic spectrum of EYS-associated retinal disease (EYS-RD), and to discover disease-associated variants with relatively high allele frequency (1%-10%) in a nationwide Japanese cohort." (PMID 32218477, 2020). "A subset of patients was screened for mutations in retinal disease genes, and mutations in the following genes were found: three cases with USH2A; three cases with EYS; one case each with USH3A (CLRN1), DHX38, RHO, RPGR, and RP9." (PMID 33037922, 2021). "Several phenotypes have been associated with pathogenic EYS variants, such as RP and CORD; thus, “EYS-associated retinal disease (EYS-RD)” can be used as an accurate description for this disease, in consideration of the phenotypic spectrum." (PMID 32218477, 2020). "No other variants of retinal disease-associated genes were detected in these 1314 families except for DRAM2 and EYS variants with high allele frequency (HAF) in a biallelic state." (PMID 32079136, 2020).
Leber congenital amaurosis (4 papers, 2012 to 2025). Leber congenital amaurosis (LCA) is a retinal dystrophy defined by blindness and responses to electrophysiological stimulation (Ganzfeld electroretinogram (ERG)) below threshold, associated with severe visual impairment within the first year of life. "Mutations in EYS are associated with several phenotypes, such as RP, cone–rod dystrophy (CRD), and Leber congenital amaurosis (LCA), and we collectively call these phenotypes EYS-associated retinal disease (EYS-RD) here." (PMID 34689181, 2022). "These genes are known to cause: X-linked RP (RPGR), autosomal recessive RP (MAK and EYS), autosomal dominant RP (PRPF31), Stargardt disease (ABCA4), and Leber congenital amaurosis (GUCY2D)." (PMID 32000842, 2020).
retinitis pigmentosa 25 (3 papers, 2016 to 2024). Any retinitis pigmentosa in which the cause of the disease is a mutation in the EYS gene. "Mutations in EYS (OMIM 612424) leading to retinitis pigmentosa 25 (RP25) for arRP (OMIM 602772) were first reported by two groups in 2008." (PMID 32436957, 2020).
retinoblastoma (3 papers, 2016 to 2021). A malignant tumor that originates in the nuclear layer of the retina. "In human Y79 retinoblastoma cells, EYS was identified in the cytoplasm and along the ciliary axoneme." (PMID 34502064, 2021). "Consistent with RNA expression data, expression analysis by PCR of cDNA from tissues and cell lines showed that the EYS gene is only expressed in the retina and in a retinoblastoma cell line in humans." (PMID 32436957, 2020). "To examine the endogenous expression pattern of EYS protein we used Y79 retinoblastoma cells." (PMID 27846257, 2016).
Usher syndrome (3 papers, 2017 to 2025). A syndromic diseae characterized by the association of sensorineural deafness (usually congenital) with retinitis pigmentosa and progressive vision loss. "It is noteworthy though, that analysis restricted to genes known to be associated with Usher syndrome based on the clinical symptoms would have revealed only the CDH23 variants while the EYS variants would have remained undetected." (PMID 30718709, 2019). "Such mutations have been reported for different retinopathies including Usher syndrome: They may affect non-coding exons and possibly affect gene transcription, as we and others have shown for EYS-related RP12." (PMID 28469144, 2017).
Hearing impairment (2 papers, 2019 to 2021). A decreased magnitude of the sensory perception of sound. "In the proband RP-1022, who presented RP, optic neuropathy, and mild unilateral hearing impairment, the homozygous missense variant p.(Ser2983Tyr) in EYS (MIM *612424) was found; therefore, this case was reclassified as non-syndromic." (PMID 34448047, 2021). "Case 135 was found to be compound heterozygote for variants in both EYS and CDH23; he was diagnosed clinically with RP and had a mild hearing impairment." (PMID 30718709, 2019).
ciliopathy (1 paper, 2021). A genetic disorder of the cellular cilia or the cilia anchoring structures, the basal bodies, or of ciliary function. "Approximately 25% of all IRDs can be categorised as ciliopathies, but EYS is the first extracellular protein known to cause ciliopathy." (PMID 34001227, 2021). "EYS is the first extracellular protein known to cause ciliopathy, and other possible roles and interactions are still under study." (PMID 34001227, 2021).
dyslexia (1 paper, 2024). A learning disorder characterized by an impairment in processing written words. "Deletion of EYS has been found in dyslexia, but with incomplete penetrance." (PMID 38891944, 2024).
early-onset retinal dystrophy (1 paper, 2022). "The SP sequences of the CRB1 (early-onset retinal dystrophy), NDP (familial exudative vitreoretinopathy) (FEVR), FZD4 (FEVR), EYS (RP), and RS1 (XLRS) genes were affected." (PMID 36362148, 2022).
gastric cancer (1 paper, 2022). A primary or metastatic malignant neoplasm involving the stomach. "We also found six genes in MSS tumors (EYS, FAT4, FSIP2, PCDHA1, RAD50, and RECQL4) and two in MSI tumors (EXO1 and FSIP2) that were clonally mutated in multiple patients and have not been previously identified as drivers of gastric cancer or other cancers." (PMID 36970058, 2022).
Hypertension (1 paper, 2023). The presence of chronic increased pressure in the systemic arterial system. "Up until now, the association of other genes, such as ATXN7L3B, LOC646588, EYS, MGEA5, and SAE1, with hypertension had not been extensively researched, but they may also serve as candidates to be further verified." (PMID 36869404, 2023).
kidney cancer (1 paper, 2024). Primary or metastatic malignant neoplasm involving the kidney. "A significant reduction in TMEM25 expression was observed among the mutation groups of BAP1, UNC80, EYS, SETD2 and XIRP, compared with the wild group, as BAP1 and SETD2 are commonly occurring mutation types in kidney cancer and have poor prognosis." (PMID 38189809, 2024).
lumbar disc herniation (1 paper, 2019). "Therefore, in combination with our experimental results, we propose for the first time that EYS polymorphism was associated with the risk of lumbar disc herniation in Han Chinese population." (PMID 31359629, 2019).
macular holes (1 paper, 2025). A hole in the macula of the retina. "When comparing the prevalence of specific genes and comorbidities, we found the following associations in AR RP: CRB1 was statistically associated with ERM (p = 0.003), EYS with cataract (p = 0.001), PROM1 with CNV (p = 0.0026), and USH2A with macular hole (p = 0.01)." (PMID 40725401, 2025).
Obesity (1 paper, 2021). Accumulation of substantial excess body fat. "By contrast, although the human orthologs of glp-1, NOTCH4 and EYS, were associated with obesity in GWAS, they have not been causally linked to the disease." (PMID 34492009, 2021).
peripheral vascular disease (1 paper, 2023). Any disorder affecting blood flow through the veins or arteries outside of the heart. "Interestingly, EYS (eyes shut homolog) displayed a marked correlation with the primary cause of death from peripheral vascular disease." (PMID 37189830, 2023).
type 2 diabetes (1 paper, 2021). "The study revealed an excess of native Hawaiian ancestry on chromosome 6, and further single variant association tests focused on this region identified a variant in the 5’UTR region of the eyes shut homolog (EYS) gene significantly associated with type 2 diabetes." (PMID 34203440, 2021).
uveitis (1 paper, 2022). An inflammatory process affecting a part of or the entire uvea. "Genes associated with the risk of developing uveitis include ERAP1, intergenic region 2p15, IL23R, IL10-IL19, IL18R1-IL1R1, IL6R, KIF21B, and EYS." (PMID 35629038, 2022).
cancer (8 papers, 2017 to 2022). A tumor composed of atypical neoplastic, often pleomorphic cells that invade other tissues. "Although EYS has not previously been investigated in the context of prognosis, the adverse prognostic impact of APC, NOTCH1, ARID1A, and filamin A has been reported in other cancer types." (PMID 33801954, 2021).
retinopathy (7 papers, 2016 to 2025). "This study aimed to classify the phenotypes of eyes shut homolog (EYS)-associated retinopathy based on visual impairment patterns and investigate their characteristics." (PMID 40989003, 2025). "However, the pathogenic mechanisms of EYS mutations in the human retina remain unclear, due to the absence of an animal model that accurately recapitulates human EYS-associated retinopathy." (PMID 40989003, 2025). "Several candidate genes associated with CQ/HCQ retinopathy were found with exome sequencing, including RP1L1, RPGR, RPE65, CACNA2D4, EYS, RP1, IMPG1 and ABCA4." (PMID 38548946, 2024). "Patient 1153 was excluded from this report because her retinopathy was possibly affected by both the DRAM2 and EYS variants." (PMID 32079136, 2020).
tumor (5 papers, 2014 to 2022). "We created the Neo-fs index—defined as the number of marker proteins with low expression among the five independent prognosticators (APC, NOTCH1, ARID1A, EYS, and filamin A)—to develop a simple, practical biomarker with potential prognostic or predictive value reflective of tumor biology." (PMID 33801954, 2021). "Conversely, we found the previously identified PCa driver gene LRP1B (12/17) and new candidate genes TTC28 (16/27), CADM2 (12/16), LSAMP (11/16), EYS (16/18), PTPRD (12/18), PACRG (5/6) and PDE4D (12/17) to be predominately interrupted in tumours from African patients." (PMID 36045381, 2022). "AGBL4, ROBO2, EYS and RYR3 appeared to have two insertions in distinct sites in the same tumour, though these could be insertions at a single rearrangement junction, since this is known to occur." (PMID 26159513, 2015). "In normal kidney tissue ANKS1B, ACOT6, EYS, CHRNA6, MT1G and UTY were up regulated in smokers in comparison to non-smokers; however, these genes tended to be down regulated in smokers versus non-smokers in ccRCC tumor tissue." (PMID 24479813, 2014).
myopathy (2 papers, 2020 to 2022). A disease of the muscle in which the muscle fibers do not function properly. "Replication studies in a small population have identified three SNPs, rs9342288, rs1337512, and rs3857532, in the eyes shut homolog (EYS) on chromosome 6, suggestive of an association with the risk of severe statin myopathy." (PMID 36554779, 2022).
genetic diseases (1 paper, 2016). "Our study not only expands the spectrum of EYS mutations for arRP in the Indian population but also shows that WES can be an effective tool for identifying causative mutations in RP patients and diagnosing genetic diseases." (PMID 26787102, 2016).
EYS also shares sentences with these, for which no sentence is quoted: night blindness (4 papers); macular degeneration (3); Stargardt disease (3); Macular dystrophy (2); age-related macular degeneration (1); alcohol dependence (1); Alzheimer disease (1); Astigmatism (1); Bietti crystalline dystrophy (1); cardiomyopathy (1); cataract (1); choroideremia (1); colorectal cancer (1); Familial exudative vitreoretinopathy (1); glaucoma (1); heart failure (1); hereditary ataxia (1); Hypomyelinating leukodystrophy (1); invasive breast carcinoma (1); melanoma (1); metabolic disease (1); Optic neuropathy (1); prostate adenocarcinoma (1); retinitis (1); sarcoma (1); Shwachman-Diamond syndrome 1 (1); Smith-Lemli-Opitz syndrome (1); Thrombocytopenia (1); Usher syndrome type 2A (1); X-linked juvenile retinoschisis (1).